CTLA4 (cytotoxic T-lymphocyte associated protein 4)
Diseases named in the same sentence as CTLA4 in open-access papers (continued):
Sharing a sentence is not in itself a finding about the gene and the disease.
myasthenia gravis (28 papers, 2005 to 2025). Myasthenia gravis (MG) is a rare, clinically heterogeneous, autoimmune disorder of the neuromuscular junction characterized by fatigable weakness of voluntary muscles. "CTLA4 alterations have also been associated with an increased susceptibility to myasthenia gravis (MG)." (PMID 40149457, 2025). "We fine mapped the CLTA4 locus in myasthenia gravis and demonstrated for the first time that causal alleles result in low expression of CTLA4 in CD4+ T‐cells." (PMID 34279044, 2021). "Relating to our findings previous studies identified CTLA4 SNP rs733618 to be significantly associated with myasthenia gravis." (PMID 32545568, 2020). "Myasthenia gravis and encephalitis were associated with anti-PD-1 whereas other neurologic AEs were associated with anti-CTLA-4." (PMID 31118078, 2019). "Interestingly, these events were differentially associated either with single-agent anti-PD-1/PD-L1 (myasthenia gravis and encephalitis) or anti-CTLA-4 (GBS and meningitis), and were generally increased by combination ICI therapy." (PMID 31118078, 2019). "A previous study indicated that SNP rs4553808 of CTLA4 is associated with human myasthenia gravis by involvement in transcriptional binding activity for Nuclear Factor I and c/EBPbeta, and G allele of rs4553808 was less frequent in patients with myasthenia gravis than in healthy controls." (PMID 31766247, 2019). "These SNPs overlapped with gene promoter and enhancer elements revealing a potential disease mechanism through altered gene expression of CTLA4 in LO myasthenia gravis disease." (PMID 34279044, 2021). "Neuromuscular junction dysfunction (myasthenia gravis) was over-reported in patients treated with anti-PD-1/PD-L1 compared with anti-CTLA-4 (ROR 3.9, 95% CI 2.3–6.8)." (PMID 31118078, 2019). "A Murine B6 model suggests that anti-CTLA-4 treatment stimulates AChR auto-antibody production and enhances the T cell response to provoke severe autoimmune myasthenia gravis." (PMID 28716137, 2017). "Patients with AITD and myasthenia gravis had an aberrant expression of the CTLA-4 products, with high levels of sCTLA-4 and low levels of the intracellular form." (PMID 15762980, 2005). "The most common irAEs in which autoantibodies have been described are found in 1) anti-CTLA-4 treatment (thyroid dysfunction), 2) anti-PD-1 treatment (myasthenia gravis/myopathy), and 3) anti-PD-L1 therapies (diabetic ketoacidosis), although with fewer reports than the former therapies." (PMID 35433707, 2022). "In particular, myasthenia gravis is considered an emerging side effect of immunotherapies, and in the literature, there are many case reports that consider myasthenia as a possible complication of anti-PD-1, anti-PD-L1, or anti-CTLA-4 therapy." (PMID 35372076, 2022). "Myasthenia gravis can spontaneously develop in CTLA-4 knockout mice." (PMID 33604462, 2021). "Evidence from Caucasians supported a genetic predisposition of CTLA4 to myasthenia gravis (MG), but the contribution in East Asians has not been established." (PMID 25003519, 2014). "However in the GWAS catalog FLI1 has a significant association with Vitiligo, when the onset age is not taken into account, and CTLA4 is found associated with different GWASs (not studied here) for both Myasthenia gravis and Vitiligo." (PMID 37809097, 2023). "Moreover, specific class–event associations were highlighted by Johnson who showed that encephalitis and myasthenia gravis were mainly related to treatments with anti-PD-1/PD-L1 agents, while GBS and meningitis were mainly related to anti-CTLA-4 combination therapies." (PMID 35372076, 2022).
lymphoproliferative disorder (27 papers, 2003 to 2025). "The role of CTLA-4 in the control of auto-reactive T cells has been demonstrated in CTLA-4 deficient mice, who developed a lethal form of lymphoproliferative disorder." (PMID 33920505, 2021). "Deficiencies in CTLA-4 have been associated with lymphoproliferative disorders and the development of severe T-cell-mediated autoimmune diseases, which is why CTLA-4 is recognized as a key molecular target governing Treg-mediated suppression." (PMID 29535728, 2018). "In vivo studies have shown that CTLA-4-deficiency in mice causes severe lymphoproliferative disorders, promoting a Th2 phenotype while a Th1 phenotype is required for efficient anti-tumor immunity." (PMID 24348481, 2013). "The CTLA-4 pathway first came to the attention of the immunological community in 1995 with the discovery that mice deficient in Ctla-4 suffered a fatal lymphoproliferative syndrome." (PMID 23849743, 2013). "CTLA-4 deficient mice show severe lymphoproliferative disorders with T helper sub-population skewed toward the Th2 phenotype." (PMID 14575153, 2003). "To date, heterozygous germline variants in CTLA4, leading to haploinsufficiency, have been associated with several immunological disorders, including hypogammaglobulinemia, multi-organ autoimmunity, lymphoproliferative disorders, and enlarged lymphoid organs." (PMID 40149457, 2025). "The lineage-specific deletion of mouse Ctla4 in Treg cells alone is enough to largely recapitulate the fatal lymphoproliferative disorders connected to germline mutations in the Ctla4 gene, implying that CTLA-4 is principally involved in Treg cell functionality." (PMID 35954362, 2022). "A CTLA-4 knockout experiment in mice showed a lymphoproliferative disorder since CTLA-4 elevates the T cell activation threshold, eliminating the immune response to some tumor antigens." (PMID 35054524, 2022). "CTLA-4−/− mice developed a severe lymphoproliferative disorder and mice die between 18 and 28 days of age." (PMID 32351508, 2020). "Introduction of CTLA-4-sufficient Tregs reverts the lymphoproliferative disorder and prevents early lethality in CTLA-4 knockout mice, whereas blocking of CTLA-4 on Tregs completely abrogates their suppressive function." (PMID 26870040, 2016). "The importance of CTLA-4 regulation is emphasized by the lethal lymphoproliferative disorder seen in CTLA-4−/− mice." (PMID 26276872, 2015). "Accordingly, CTLA-4 knockout mice were shown to develop lymphoproliferative disorder with excessive accumulation of activated T cells and preclinical study with antibodies against CTLA-4 demonstrated tumor cells suppression." (PMID 25918658, 2015). "Whereas ctla-4 KO mice died from a lethal lymphoproliferative disorder at a very young age, some colonies of pd-1 KO mice lived over a year before expressing lupus-like symptoms." (PMID 24348481, 2013). "It has been reported that the knockout of CTLA-4 resulted in a lymphoproliferative disorder and death in mice, which indicated a very important role of CTLA-4 in negative regulation of T cell activation." (PMID 21992110, 2011). "Indeed, CTLA-4 is critical for “tolerance”, a fact substantiated by the experimental finding that the biallelic deletion of the Ctla4 gene led to massive lymphoproliferative disorder in mice." (PMID 36829496, 2023). "In the mouse model, Ctla4 haploinsufficiency has not been reported to cause a phenotype but Ctla4-/- mice develop a lethal lymphoproliferative disorder by 3-4 weeks of age." (PMID 35154081, 2021). "In fact, CTLA-4 inhibition causes a major immunostimulation, as experimentally shown in CTLA-4 knock-out (KO) mice, which die after few months due to uncontrolled lymphoproliferative disorders and, in a clinical setting, by the reactivation of T cell-mediated tumor rejection." (PMID 33935977, 2021).
lymphoproliferative disorder (continued). "Furthermore, IL-2 has been shown to upregulate CTLA-4 (cytotoxic T-lymphocyte-associated protein 4; CD152), and CTLA-4-deficienciy leads to a fatal lymphoproliferative disease that is more aggressive than the lymphoproliferative disorders caused by either IL-2 or Fas deficiency." (PMID 16759382, 2006). "CTLA-4 has a strong inhibitory effect on T cell function, and mice lacking CTLA-4 exhibit lymphoproliferative disorders." (PMID 40027134, 2025).
malaria (25 papers, 2009 to 2025). Malaria is a serious and sometimes fatal disease caused by a parasite that commonly infects a certain type of mosquito which feeds on humans. "In malaria-infected individuals, the overexpression of CTLA-4, PD-1, and GITR in T cells is associated with impaired parasite clearance." (PMID 34592958, 2021). "Our results identify specific clusters of CTLA-4+PD-1+CD4+ T cells which are associated with malaria complications." (PMID 29555909, 2018). "Therefore, in this study, we directly compared the roles of the CTLA-4 and PD-1/PD-L pathways during acute infection with a virulent rodent malaria parasite, PbA in ECM-susceptible (C57BL/6) and ECM-resistant (BALB/c) mice." (PMID 22319445, 2012). "Also, the increased expression of CTLA-4 on Tregs in the symptomatic children suggests that immune regulation associated with clinical malaria may affect cellular activation, consequently, affecting the downstream development of anti-malaria immunity." (PMID 30005684, 2018). "Moreover, since the number of CTLA-4+ Tregs is positively associated with parasitemia, it may suggest the involvement of this receptor on the outcome of human malaria." (PMID 20224778, 2010). "A functional deficit of Treg cells, characterized by reduced expression of CTLA-4 (cytotoxic T lymphocyte antigen 4) and FoxP3 (forkhead box P3 transcription factor), was observed in studies involving the Fulani ethnic group that present low susceptibility to clinical malaria by P. falciparum." (PMID 20224778, 2010). "Although not significant, we observed a reduced frequency of CD4+C25+FoxP3+ expressing Ki-67 and CTLA-4 among patients with a previous malaria exposure." (PMID 40726977, 2025). "We found that PD-1+, 4-1BB+, LAG-3+, KLRG1–, PLZF–, CTLA4+, and Siglec-7– NK cells were increased in individuals with malaria experience." (PMID 40337867, 2025). "Examining malaria-experienced individuals for common markers across all assays, 4-1BB+, CTLA-4+, CX3CR1+, NKG2C+, TIM-3+, and Siglec-7– NK cells were enriched for IL-10 production." (PMID 40337867, 2025). "Consistent with scRNAseq data, at day 0 during malaria, there was significantly higher proportion of Tr1 cells expressing CD120b, CTLA-4, TIM-3, PD1, CD38 and ICOS." (PMID 37968278, 2023). "Despite these protective responses, asymptomatic malaria featured an immunosuppressive transcriptional signature with upregulation of pathways involved in the inhibition of T‐cell function, and CTLA‐4 as a predicted regulator in these processes." (PMID 35475529, 2022). "Supporting this finding, a previous study showed that CTLA-4 activity inhibits T cell-mediated parasite tissue sequestration in a mouse model of malaria, and thereby limits malaria-induced immune pathology." (PMID 31134084, 2019). "The levels of CTLA4+ Tregs in children with asymptomatic malaria were significantly lower than in those with clinical malaria (P = 0.0174) but comparable with the control group." (PMID 30005684, 2018). "Previous studies in VL and malaria have shown the role of PD-1 and CTLA-4 in pathogenesis due to the induction of dysfunctional T cells." (PMID 29915577, 2018). "Cluster group II showed a higher expression of CTLA-4 and PD-1 and was more frequent in children with complicated malaria than in children with uncomplicated malaria." (PMID 29555909, 2018). "Significantly, flow cytometric analysis and automated multivariate clustering, has revealed more frequent expression of CTLA-4 or PD-1 on CD4+ T cells from children with complicated malaria compared to uncomplicated malaria." (PMID 30631323, 2018). "Cluster group I showed a lower expression of PD-1 and CTLA-4, compared to background, and was more abundant in children with uncomplicated malaria." (PMID 29555909, 2018). "The higher frequencies of PD-1+ and CTLA-4+ CD4+ T cells are therefore most likely a consequence of the very strong T cell activation in complicated malaria, which then contributes to the more severe symptoms of the patients." (PMID 29555909, 2018).
malaria (continued). "Additional longitudinal and functional studies are urgently needed to further investigate if and how CTLA-4+PD-1+CD4+ T cells display a detrimental effect in malaria or rather prevent a worse course of disease." (PMID 29555909, 2018). "It has recently been shown that Tregs expressing CTLA-4 in murine models of malaria interfere with the acquisition of long-term immunity to malaria infections." (PMID 30005684, 2018). "Children with complicated malaria had higher frequencies of CTLA-4+ or PD-1+ CD4+ T cells than children with uncomplicated malaria." (PMID 29555909, 2018). "In summary, these data show that malaria-induced PD1+CTLA4+CD4+ T cells inhibit the proliferation of other T cells in a cell extrinsic manner." (PMID 27802341, 2016). "We showed that in malaria patients, high numbers of T cells expressed the coinhibitory receptors CTLA4 and PD1." (PMID 27802341, 2016). "The PD1+CTLA4+ T cells in our malaria patients were clearly distinct from natural Tregs as they did not express Foxp3 or CD25, nor were they CD49b+LAG3+, which are recently identified markers for Tr1 cells." (PMID 27802341, 2016). "Flow cytometric analysis showed that the majority of PD1+CTLA4+CD4+ T cells in malaria patients were Foxp3- and CD25-, which indicates that they were not Foxp3+ natural Tregs (nTregs)." (PMID 27802341, 2016). "Even more surprising, we found that although PD1+ CTLA4+CD4+ T cells contained the majority of malaria-specific T cells, they showed, at the same time, cell-extrinsic suppressor activity and actively downregulated T cell proliferation." (PMID 27802341, 2016). "Surprisingly, subsequent experiments showed that the PD1+CTLA4+CD4+ Teff cells in malaria patients had an acquired extrinsic regulatory function by which they suppressed the P. falciparum-specific and polyclonal proliferation of other T cells." (PMID 27802341, 2016). "Surprisingly, despite the high expression of coinhibitory receptors, malaria-specific effector function was predominantly found in the PD1+CTLA4+CD4+ T cell population." (PMID 27802341, 2016). "The percentage of CTLA4+CD4+ T cell was significantly higher in patients with cerebral malaria than in patients with uncomplicated malaria." (PMID 27802341, 2016). "In support of this, we and other groups have shown that in experimental murine malaria, conventional T cells strongly express the coinhibitory receptors CTLA4 and PD1." (PMID 27802341, 2016). "Taken together, our data support the notion that the observed dysfunction of P. falciparum-specific T cells during acute malaria can be attributed, at least in part, to the upregulation of CTLA4 and PD1." (PMID 27802341, 2016). "Not only CD4+ T cells, but also more CD8+ T cells from malaria patients expressed CTLA4, compared to healthy controls (P<0.001), although the frequencies were much lower than for CD4+ T cells (6.5% versus 23%)." (PMID 27802341, 2016). "We next examined the ability of PD1+CTLA4+CD4+ T cells in malaria patients to produce cytokines in response to plasmodial antigens." (PMID 27802341, 2016). "An indirect evidence of the role of this receptor in experimental malaria has been demonstrated by the in vivo blockade of CTLA-4 using specific monoclonal antibody, leading to an exacerbation of P. berghei-mediated immunopathology." (PMID 20224778, 2010). "P. vivax-infected individuals presented a significant increase of circulating GITR+ (P = 0.0119) and CTLA-4+ Treg cells (P = 0.0026), when compared to malaria-naïve donors." (PMID 20224778, 2010). "Furthermore, a study on malaria has demonstrated that Tregs impede protective immunity through CTLA-4 and that CTLA-4 blockade leads to significantly enhanced frequencies of Th1 and Th17 cells." (PMID 39456030, 2024). "Furthermore, our analysis identified significant downregulation of genes involved in the control of cell proliferation in asymptomatic malaria and predicted the inhibitory receptor CTLA‐4 as the upstream regulator responsible for these processes." (PMID 35475529, 2022).